KRT10 (keratin 10)
Diseases named in the same sentence as KRT10 in open-access papers (continued):
Sharing a sentence is not in itself a finding about the gene and the disease.
tumor (continued). "Immunocytochemically, tumor cells from all cases examined did not express keratin 10, while strong positivity to anti-keratin 5, 8, and 18 antibodies, and anti-UEL antibody was observed." (PMID 15357873, 2004). "Tumor features were assessed by the evaluation of spheroid’s growth and proliferative ability in vitro, and the expression of E-Cadherin, a negative marker of the Epithelial to Mesenchymal Transition (EMT), KRT13, and the differentiation marker Keratin 10 (KRT10)." (PMID 37443031, 2023). "In addition to enrichment for keratins found in normal spheroid stem cells (KRT13, 23, 80, 78, and 4), a group of other keratin genes that includes KRT10, 19, 6, 75, 16, 79, 3, and 82 were enriched in the cSCs relative to the non-cSC population of tumor spheroids." (PMID 34360875, 2021). "Interestingly, FC2 displayed the highest correlation with epithelial cells and showed specific expression of tumor epithelial markers KRT8, KRT10, and KRT18, as well as the EMT markers SNAI1 and SNAI2, suggesting that FC2 may have the tumor‐like aggressive potential." (PMID 34459128, 2021). "In addition, levels of the differentiation markers KRT10 and KRT14 and senescence marker SA‐β‐gal were upregulated at the boundary of the tumor in UVB‐exposed wild‐type mice, suggesting that SASP activation and carcinogen‐stimulated tumor formation resulted from cell senescence." (PMID 31755176, 2020).
cancer (30 papers, 2004 to 2025). A tumor composed of atypical neoplastic, often pleomorphic cells that invade other tissues. "The decreased tumorigenicity was mirrored by a reduction in the Ki67 proliferative index and increased differentiation, as indicated by the large increase of cancer cells with the KRT10 marker expression." (PMID 36797248, 2023). "Along with common keratins (KRT13/23/80/78/4) in normal stem cells, unique keratins (KRT10/19/6C/16) were enriched in cancer stem-like cells." (PMID 34360875, 2021). "Cancer line analysis indicated significant downregulation of five cytoskeleton proteins, keratins (KRT2, KRT9, KRT1, KRT10)." (PMID 37377864, 2023). "Protective mechanisms included defense against infection (Alpha-1-B glycoprotein A1BG, Serpin family A member 1 SERPINA1, Transthyretin TTR), neuroprotection (TTR), and reduced risks of inflammation, infections, and cancer (SERPINA1, Keratin 10 KRT10)." (PMID 36145440, 2022). "Interestingly, KRT10, which is considered to be SKCM-specific keratin, was detected in all cancers including brain and blood cancers." (PMID 35267493, 2022). "For DCIS tissues, compared with both DCIS cancer-adjacent and normal tissues, we detected four up-regulated (GAPDH, HSPA9, CCT4, and SCPEP1) and 48 down-regulated proteins (including KRT10, APOA1, ALDH1A1, and others) in DCIS tissues." (PMID 33194682, 2020). "Levels of keratins, type I cytoskeletal 16 (KRT16), 9 (KRT9), and 10 (KRT10), as well as complement factor H‐related protein 4 (CFHR4) and 1 (CFHR1), had higher levels in plasma samples from patients with cancer in the right colon (with fold changes between 6.2‐13.0)." (PMID 32452655, 2020).
infection (29 papers, 2009 to 2025). The state of being infected such as from the introduction of a foreign agent such as serum, vaccine, antigenic substance or organism. "The co-expression of Krt5 and Krt10 was unique to infection-specific clusters (clusters 0 and 6)." (PMID 38767331, 2024). "However infection of these cells with VZV significantly reduced KRT10 gene expression." (PMID 24497829, 2014). "At both 24 and 48 hrs post infection the expression of KRT10 was reduced in VZV infected nTERTs compared to the mock infected controls and pre-treatment of the viral inoculum with PAA, which inhibits VZV DNA polymerase and viral replication restored KRT10 expression." (PMID 24497829, 2014).
genetic skin diseases (2 papers, 2019 to 2020). "Keratinopathic ichthyoses (KI) are a group of genetic skin diseases due to mutations in keratin genes KRT1, KRT2, and KRT10 encoding keratins 1, 2 and 10 (K1, K2, K10), respectively, expressed in suprabasal epidermis." (PMID 33081034, 2020). "Ichthyosis with confetti (IWC) is a genodermatosis associated with dominant‐negative variants in keratin 10 (KRT10) or keratin 1 (KRT1)." (PMID 31638346, 2019).
benign tumors (1 paper, 2021). "MCPIP1 immunoreactivity was higher than that in the adjacent skin, particularly in cells that also expressed keratin 10 (KRT10), which is a characteristic for differentiating benign tumors." (PMID 34903245, 2021).
metabolic disorders (1 paper, 2013). "As we know, PKB and PKC pathways could regulate glucose homeostasis; thus, the impairment of PKB and PKCδ by keratin 10 might induce potential metabolic disorders." (PMID 23671866, 2013).
KRT10 also shares sentences with these, for which no sentence is quoted: atopic dermatitis (6 papers); skin disorder (5); skin tumors (5); dysplasia (4); epidermolysis bullosa (4); epidermolysis bullosa simplex (3); Erythema (3); pachyonychia congenita (3); acne (2); congenital reticular ichthyosiform erythroderma (2); COVID-19 (2); diabetes (2); diabetic foot ulcer (2); epidermolytic nevus (2); Erythroderma (2); lupus (2); metastatic tumor (2); oral mucosal ulcers (2); skin cancer (2); superficial epidermolytic ichthyosis (2); thymoma (2); age (1); AIDS (1); allergic disease (1); aniridia (1); annular epidermolytic ichthyosis (1); aplasia cutis congenita (1); asthma (1); autoimmune disease (1); autosomal dominant disease (1).
A further 68 diseases each share a sentence with KRT10 in 1 paper.